TLR7 (toll like receptor 7)
Diseases named in the same sentence as TLR7 in open-access papers (continued):
Sharing a sentence is not in itself a finding about the gene and the disease.
psoriasis (continued). "Of the mass spectrometry‐identified SHP2‐interacting proteins, we focused on TLR7 because it has been reported to participate in the development of psoriasis." (PMID 34936223, 2022). "Taken together, our findings connecting SHP2 and TLR7 highlighted the importance of SHP2 as a positive regulator of inflammation in psoriasis and probably in other autoimmune diseases." (PMID 34936223, 2022). "Collectively, these results demonstrated that phosphor‐TLR7 Y1024 plays an important role in the progression of psoriasis." (PMID 34936223, 2022). "IMQ is an agonist of the Toll-like receptor 7/8 ligand, and its application histologically closely resembles human psoriasis." (PMID 36741386, 2022). "Resiquimod, a chemically synthesised substance, specifically binds to TLR7/8, and has been successfully used in experimental models for inflammatory skin pathologies, e.g., psoriasis models." (PMID 35453606, 2022). "Previous studies have shown that TLR7 activation leads to upregulation of pro‐inflammatory cytokines, accelerating the development of psoriasis." (PMID 34936223, 2022). "Skin macrophage autophagy also protects against the treatment of mice with the TLR7 agonist imiquimod, a model of psoriasis, by inhibiting NF-κB492." (PMID 37425656, 2022). "SHP2 overexpression or overactivation (e.g., as observed in IMQ or psoriasis) maintains excessive activation of TLR7/NF‐κB signaling and accelerates psoriasis‐like skin inflammation." (PMID 34936223, 2022). "In IMQ-induced psoriasis, TLR-7/8 gets activated and initiates Th-17 cells specific cytokines in response to the IL-23 overproduction by plasmacytoid dendritic cells." (PMID 35991888, 2022). "It is well known that IMQ, a TLR7/8 ligand and potent immune activator, can induce psoriasis‐like skin inflammation." (PMID 35716036, 2022). "Further studies should be performed in other skin resident cells (LCs, melanocytes, and keratinocytes) expressing TLR7 upon TLR3 activation during psoriasis with AZT." (PMID 33510592, 2021). "Imiquimod (IMQ), a TLR7 agonist, has been applied to promote psoriasis-like skin inflammation via the IL-23/IL-17 axis in murine experiments." (PMID 34733291, 2021). "SOD3-overexpressing MSCs specifically prevented the development of psoriasis in a mouse model of imiquimod (IMQ)-induced psoriasis-like inflammation via the inhibition of the TLR7/MAPKs/NF-κB axis and the activation of the adenosine receptor." (PMID 33805942, 2021). "IMQ, a ligand of TLR-7/8, induces psoriasis-like dermatitis in mouse mimicking human psoriasis pathogenesis and systemic inflammation, including elevated levels of IL-23/IL-17A-Th17 axis pro-inflammatory cytokines and chemokines 34-36." (PMID 33391503, 2021). "Our early study demonstrated that imiquimod can also act on nociceptor TLR7 to elicit pruritus, a remarkable clinical feature of psoriasis." (PMID 34950149, 2021). "For example, paeonol inhibits the maturation and activation of DCs by reducing MyD88 and TLR8 proteins in the TLR7/8 signalling pathway, and ultimately alleviates psoriasis-like skin lesions in BALB/c mice." (PMID 35095512, 2021). "The antibiotic azithromycin can improve the severity of IMQ-induced mouse psoriasis by interfering with the lysosomal processing of TLR7 maturation and signaling in DC." (PMID 34361107, 2021). "Imiquimod (IMQ), an agonist of Toll-like receptor 7/8 ligand, induced a dermatitis in mice closely resembling human psoriasis." (PMID 33081840, 2020). "TLRs play an important role in innate immune responses, and in psoriasis, activation of TLR7 and TLR9 via autoimmune plasmacytoid dendritic cell activation releases interferon-α, which further stimulates mDCs to secrete IL-23." (PMID 32823524, 2020). "Studies in IL-23- or imiquimod (IMQ; a Toll-like receptor 7/8 agonist)-induced mouse models of psoriasis show that psoriatic inflammation is impaired in IL-22- and IL-17-deficient mice, thereby confirming the role of the IL-23/IL-17 axis." (PMID 32355189, 2020).
psoriasis (continued). "In this study, we investigated the possible roles of TLR2 in the development of psoriasis, using a mouse psoriasis model induced by imiquimod, a ligand for TLR7." (PMID 33202847, 2020). "IMQ, an agonist of Toll-like receptor 7/8 ligand, was found to be able to induce a dermatitis in mice closely resembling human psoriasis." (PMID 33081840, 2020). "Given its unique attributes, this study was designed to characterize inflammatory skin reactions of this animal to topical application of imiquimod, a toll-like receptor 7 and 8 agonist that triggers psoriasis-like skin reaction." (PMID 32891181, 2020). "The IMQ-induced mouse model for psoriasiform dermatitis is one of the most widely used mouse models in recent research studies on psoriasis, as psoriasis mediated by the IL-23/Th17 axis can be triggered by this TLR7 agonist." (PMID 33536902, 2020). "When topically applied as a cream, imiquimod, a TLR7/8-stimulating compound, induces dermatitis that closely mimics psoriasis with typical hallmarks such as erythema, skin thickening, scaling, and epidermal alterations such as acanthosis and parakeratosis." (PMID 32106600, 2020). "IMQ, an agonist of Toll-like receptor 7/8 ligand, is widely topically applied on the skin of mouse to induce psoriasis-like lesions closely resembles human psoriasis in phenotypic and histological characteristics." (PMID 32493482, 2020). "Making use of its mode of action in activating TLR7, imiquimod-induced psoriasis is frequently used in a mouse model for psoriasis." (PMID 32823524, 2020). "The results indicated that the inhibition of the TLR7/8–MyD88–NF-κB pathway was relevant to the protective effects of EPD on IMQ-induced psoriasis." (PMID 31181689, 2019). "Imiquimod (IMQ), a synthetic agonist for toll-like receptor 7 (TLR7), is a potent immune response activator and induces psoriasis-like skin inflammation." (PMID 31447855, 2019). "Th17 cells are major players in imiquimod-induced psoriasis as well, and pDCs have been reported to secrete pro-Th17 cytokines (e.g., IL-6) in response to TLR7 ligation." (PMID 31105556, 2019). "Psoriasis-like lesions can be induced on mouse skin by topical application of imiquimod, a TLR7 agonist." (PMID 31105556, 2019). "Accordingly, the pathogenesis and progress of psoriasis were closely related to TLR7/8-MyD88-NF-κB and NLRP3 pathways." (PMID 31181689, 2019). "While EAU in animals was used as a model of human uveitis, treating mice with innate TLR7/8 ligand IMQ rapidly induces dermatitis closely resembling human psoriasis." (PMID 31616442, 2019). "IL-17 producing ILC3 are proposed to be involved in plaque formation in a psoriasis mouse model based on the topical application of the Toll-like receptor 7 (TLR7) agonist imiquimod." (PMID 31781103, 2019). "It was worth noting that all of these changes were obviously reversed by EPD treatment, which provided evidence that TLR7/8–MyD88–NF-κB signaling was involved in the therapeutic action of EPD on psoriasis." (PMID 31181689, 2019). "A widely used psoriasis-like inflammation mouse model relies on the effect of the TLR7/8 agonist imiquimod, and is thus in support of the TLR7/8 disease initiation model." (PMID 30909615, 2019). "We used the TLR7 agonist Imiquimod (IMQ) to induce a psoriasis-like skin disease in mice and found a strong downregulation of IL-22BP in the affected skin as well as in the lymph nodes of animals treated with IMQ." (PMID 29572462, 2018). "This is further supported by the observations that de novo psoriasis or pre-existing psoriasis can be triggered and/or aggravated by IFNα therapy and the TLR7 agonist imiquimod." (PMID 30555460, 2018). "We then assessed the expression of TWEAK and Fn14 in the skin in experimental psoriasis induced by the TLR7/8 agonist Imiquimod (IMQ) that promotes histological features seen in human psoriasis, including acanthosis, papillomatosis and parakeratosis." (PMID 28530223, 2017).
psoriasis (continued). "In IMQ-induced psoriasis model, dendritic cells are stimulated by TLR7/8 ligand (IMQ) and produce IL-12 and IL-23, which lead to accelerate Th1 and T17 cell differentiation, respectively." (PMID 28761880, 2017). "Psoriasis is a chronic inflammatory autoimmune disease that can be initiated by excessive activation of endosomal toll-like receptors (TLRs), particularly TLR7, TLR8, and TLR9." (PMID 28894754, 2017). "In a phase 2 clinical trial in patients with moderate to severe psoriasis, immune modulatory oligonucleotide- (IMO-) 3100, an antagonist of TLR7 and TLR9, was associated with a reduction in Psoriasis Area Severity Index (PASI) score." (PMID 28894754, 2017). "Epicutaneous application of Aldara cream containing the TLR7 agonist imiquimod (IMQ) to mice induces skin inflammation that exhibits many aspects of psoriasis, an inflammatory human skin disease." (PMID 27222343, 2016). "In mice, topical application of TLR7/8 agonist IMQ leads to a skin disorder resembling human psoriasis." (PMID 26999594, 2016). "Daily application of the TLR7/8 agonist imiquimod cream(Aldara®) on mouse back skin induces skin inflammation that stronglyresembles human psoriasis in terms of phenotypic and histological features." (PMID 21611195, 2011). "Given that abnormal activation of TLR7 has been clearly implicated in the pathogenesis of psoriasis, this post-translational modification may become a new target for psoriasis research by regulating the activity of the TLR7 signaling pathway." (PMID 40959086, 2025). "In this regard, it is interesting to notice that our in vitro model of psoriasis is based specifically on the capacity of IMQ to function as a selective antagonist for the Toll-like receptor-7 (TLR7) present on the surface of macrophages, lymphocytes, and dendritic cells." (PMID 40005020, 2025). "This could explain why imiquimod, a TLR7/8 agonist and a potent inducer of these cytokines, could induce psoriasis mouse model by its topical application on mouse skin through induction of IL-23/IL-17 axis." (PMID 41254515, 2025). "Additionally, the TLR7-NF-κB pathways are activated in both IMQ-induced psoriasis-like skin inflammation in mice and in normal human epidermal keratinocytes treated with IMQ." (PMID 40873769, 2025). "Therefore, we aimed to compare the immunomodulatory effects of anti-IL-2/IL-2 complex to free IL-2 on induced psoriasis-like skin inflammation induced in mice by the TLR7 agonist imiquimod." (PMID 41254515, 2025). "Furthermore, SHP2 promotes the ubiquitination of toll‐like receptor 7 (TLR7) and NF‐κB‐mediated psoriasis‐like skin inflammation by dephosphorylating TLR7 in macrophages." (PMID 40757098, 2025). "Furthermore, SHP2 has been shown to exacerbate psoriasis-like skin inflammation in mice through processes such as NETosis or TLR7 activation." (PMID 38429819, 2024). "Furthermore, psoriasis-like dermatitis led to eosinophil degranulation and immunological changes in the small intestine in a TLR7-dependent manner." (PMID 38689088, 2024). "In addition, utilising human samples from patients with psoriasis for similar studies will further validate the clinical application of the TLR7/c-Rel signalling pathway as a potential target for therapeutic development for psoriasis." (PMID 39586195, 2024). "Given that c-Rel deficient DCs are unable to produce inflammatory cytokines including IL-1β and IL-6, we hypothesised that the TLR7/c-Rel signalling axis in DCs regulated the induction of naïve T cells to differentiate into Th17 cells during psoriasis." (PMID 39586195, 2024). "Furthermore, rutaecarpine improves imiquimod-induced psoriasis-like dermatitis by modulating the nuclear factor kappa-light-chain-enhancer of activated B cells (NF-κB) and toll-like receptor 7 signaling." (PMID 38172219, 2024). "We hypothesized that SIRT3 diminished TLR7/8-XBP1s response and thereby ameliorated inflammation in psoriasis." (PMID 37275851, 2023).
psoriasis (continued). "SIRT3 deficiency exacerbated the TLR7/8-XBP1s response via deacetylation activity targeting XBP1s, contributing to the transcription of proinflammatory cytokines IL-23, IL-6, and TNF-α and thus promoting psoriasis progression and disease severity." (PMID 37275851, 2023). "TLR7 antagonists demonstrated promising results in psoriasis treatment." (PMID 37160878, 2023). "To better elucidate the role of neutrophils in psoriasis development, we have utilized the imiquimod (IMQ)-induced mouse model of psoriasis, which consists of the topical administration of Aldara TM cream - containing the Toll-like receptor 7 and 8 (TLR7/8) ligand IMQ (5%)." (PMID 36466913, 2022). "In this study, we first proved that TLR7 can be phosphorylated at Tyr1024 in the skin lesions of psoriatic patients and that its dephosphorylation by SHP2 accelerates TLR7 ubiquitination and promotes TLR7 activation of NF‐κB signaling, contributing to the aggravation of psoriasis." (PMID 34936223, 2022). "Thus, astilbin plays an anti‐inflammatory role in psoriasis by inhibiting maturation and activation of DCs, probably through the TLR7/MyD88 signalling pathway." (PMID 35023281, 2022). "Importantly, Tlr7 point‐mutant knock‐in mice showed an attenuated psoriasis‐like phenotype compared to wild‐type littermates following IMQ treatment." (PMID 34936223, 2022). "Interestingly, C-fiber nociceptor has been shown to activate the local IL-23/IL-17 cascade in the skin via release of neuropeptide calcitonin gene-related peptide (CGRP) in a murine model of psoriasis, induced by TLR7 agonist imiquimod." (PMID 34950149, 2021). "Steatohepatitis promotes the progression of psoriasis in patients with NASH, and obesity exaggerates the severity of psoriasiform dermatitis caused by the Toll-like receptor 7 (TLR-7) agonist imiquimod (IMQ) by promoting IL-17A and IL-22 secretion and IL-1β overexpression in HFD-fed mice." (PMID 34944732, 2021). "We next investigated whether PMN-derived NETs play a role in the imiquimod (IMQ, a TLR7 agonist)-induced experimental model of psoriasis in which topical application results in severe psoriasiform skin inflammation." (PMID 31913271, 2020). "LL37 was reported to form complexes with self-derived RNA as well as self-derived DNA, triggering TLR7 and TLR8 activation in human DCs, which may be associated with psoriasis pathogenesis." (PMID 33633744, 2020). "Generally, imiquimod was an agonist for TLR7/8, and TLR7/8 signaling was essential for innate immune response inflammatory signaling pathways, and considered to be involved in the pathology of imiquimod-induced psoriasis-like dermatitis." (PMID 31181689, 2019). "Topical application of IMQ, a TLR7/8 ligand and potent immune activator, can induce and exacerbate psoriasis, a chronic inflammatory skin disorder, and has been used as activator for valuable psoriasis animal model." (PMID 29867905, 2018). "Imiquimod (IMQ), a TLR7/8 agonist, has been used to induce psoriasis in a mouse model." (PMID 28761880, 2017). "Imiquimod, a ligand for TLR7/8, has been widely used for the topical treatment of anal warts, condyloma acuminata, basal cell carcinoma and solar keratosis; however, it can also exacerbate psoriasis in well-controlled patients." (PMID 28464025, 2017). "Imiquimod, a TLR7 agonist, can induce psoriasis-like lesions in human and mice." (PMID 25950182, 2015). "Indeed, in a case report, triggering of TLR7 via topical treatment with TLR7 ligand imiquimod was shown to induce exacerbation of psoriasis via massive induction of type I IFN signaling." (PMID 24744755, 2014). "Although the roles of TLR7 in keratinocytes in vivo remain unclear, our results suggest that keratinocytes play critical roles in the pathogenesis of several skin diseases, such as psoriasis, through TLR7." (PMID 24146965, 2013). "This may also translate into future trials where targeting TLR7, 8, and 9 may be more efficacious in treating psoriasis." (PMID 24386404, 2013).
psoriasis (continued). "In view of our findings, we suggest that the ability of imiquimod to activate keratinocytes via TLR7 could lead to psoriasis, supporting the notion that keratinocyte products influence immune activation." (PMID 24146965, 2013). "Evidence that TLR7, 8 and 9 may participate in psoriasis pathogenesis is also suggested by the ability of LL-37-RNA and DNA complexes to activate pDCs and mDCs." (PMID 24386404, 2013). "An earlier study that indicated that TLR7 may be involved in psoriasis pathogenesis made the observation that application of IMQ could induce psoriatic lesions at sites of inflammation." (PMID 24386404, 2013). "The question whether TLR agonists are involved in the pathogenesis of psoriasis is unclear, but the finding that a TLR7 agonist, imiquimod, induces psoriasis like plaques in mice indicates that TLR7 induction could play a role." (PMID 20663192, 2010). "However, imiquimod induces psoriasis largely through activation of TLR7." (PMID 39985685, 2025). "Preclinical in vivo models of psoriasis and skin inflammation in rodents often use imiquimod (IMQ, a TLR7/8 agonist) which, after application on the skin, gives rise to local inflammation characterised by erythema, swelling, scaling and thickening of the skin similar to psoriasis in the human." (PMID 39820614, 2025). "Thus, validation of our in vitro data using primary cells is extremely important and future studies using keratinocyte-specific c-Rel deficient mice are necessary to fully understand the contribution of the TLR7/c-Rel signalling axis in keratinocytes to psoriasis." (PMID 39586195, 2024). "Our study reveals a c-Rel-dependent molecular mechanism regulating DC function following TLR7 agonism that is critical for T cell-mediated hyperinflammation during psoriasis, which may be a potential link for how viral TLR7 activation is involved in worsening psoriatic disease." (PMID 39586195, 2024). "Our study highlights strong biochemical mechanism of NF-κB pathway signalling following TLR7 activation, however we acknowledge that future studies should utilise mice with a DC-specific deletion of c-Rel to further investigate the cell type specific role of TLR7/c-Rel axis in psoriasis." (PMID 39586195, 2024). "Thus, we hypothesised that the TLR7/c-Rel axis may be a signalling mechanism involved in psoriasis pathogenesis." (PMID 39586195, 2024). "Using patient data, a psoriasis mouse model and comprehensive mechanistic studies, we showed that TLR7-induced c-Rel-dependent transcription in DCs regulates inflammatory cytokine production and Th17 cell differentiation that promote skin inflammation and psoriasis development." (PMID 39586195, 2024). "Since the topical application of imiquimod, a ligand of TLR7 and TLR8, has been shown to causes a psoriasis-like pathology in mouse skin through the activation of dermal DCs and Langerhans cells, we expect β-damascone to ameliorate psoriasis, even from the viewpoint of modifications to DC functions." (PMID 36845043, 2023). "As for its direct effect on psoriasis, it has been reported that the improvement of psoriasis-like skin lesions in a mouse model occurs through the inhibition of the mRNA expression of IL-23 and the activation of dendritic cells via actions on the toll-like receptor 7/8 signaling pathway." (PMID 37631075, 2023). "Therefore, use of astilbin to control the maturation and activation of DCs by reducing MyD88 in TLR7/8 signals may be an effective strategy to treat psoriasis." (PMID 35023281, 2022). "In psoriatic skin, TLR7 also can be phosphorylated at Tyr1024 in epidermal cells, where TLR7 may be involved in the expansion of inflammation in psoriasis, exacerbating psoriasis by activating the NF‐κB pathway to upregulate the expression of multiple inflammatory factors." (PMID 34936223, 2022).